OGT (O-linked N-acetylglucosamine (GlcNAc) transferase)
Diseases named in the same sentence as OGT in open-access papers (continued):
Sharing a sentence is not in itself a finding about the gene and the disease.
glioblastoma (8 papers, 2020 to 2025). The most malignant astrocytic tumor (WHO grade IV). "Transcriptional downregulation of these specific glioblastoma associated genes due to OGT reduction indicates that OGT may be required for glioblastoma maintenance and progression which is also supported by previous reports for a variety of other cancers." (PMID 37689115, 2023). "In glioblastoma cells upon high glucose conditions, OGT is phosphorylated by hexokinase 1 at Y889, which recruits the p85α subunit of PI3K." (PMID 41005476, 2025). "OGT has been shown to regulate glioblastoma acetate metabolism by influencing cyclin-dependent kinase 5 (CDK5)-dependent ACSS2 phosphorylation." (PMID 39285476, 2024). "We found that OGT knockdown, in particular led to reduced expression of many genes with prominent roles in glioblastoma progression and cancer cell invasion." (PMID 37689115, 2023). "Another OGT target gene with a significant role in glioblastoma tumorigenesis is nicotinamide phosphoribosyltransferase (NAMPT), which is a rate-limiting enzyme of the salvage pathway to regenerate adenine dinucleotide (NAD)." (PMID 37689115, 2023). "Similar to lipid metabolism, acetate metabolism in cancer cells is also regulated by OGT/O-GlcNAc in glioblastoma (GBM)." (PMID 37838167, 2023). "Corroborating our results, a recent work demonstrated that the U87MG and T98G human glioblastoma cell lines and tissue samples from patients with GB grade IV had higher protein levels of O-GlcNAcylation and OGT compared to healthy astrocyte cells." (PMID 37835434, 2023). "OGT reduction led to significantly reduced glioblastoma cell proliferation, migration, and invasion." (PMID 37689115, 2023). "We demonstrate that OGT knockdown and chemical inhibition led to reduced glioblastoma cell proliferation and downregulation of many genes known to play key roles in glioblastoma cell proliferation, migration, and invasion." (PMID 37689115, 2023). "Additionally, O-GlcNAc transferase (OGT) and O-GlcNAc levels are elevated in glioblastoma and are required for tumor growth in vitro and in vivo." (PMID 40097417, 2025). "Finally, we found that chemical inhibition of BRD4 potentiated the effects of OGT inhibition in reducing glioblastoma cell proliferation, invasion, and migration." (PMID 37689115, 2023). "Based on these evidences, we hypothesized that BRD4 could be O-GlcNAcylated by OGT in glioblastoma which may regulate its function in transcription regulation of target genes." (PMID 37689115, 2023). "We found that OGT reduction significantly reduced AKT-Ser473P suggesting that OGT may regulate glioblastoma cell proliferation through Akt pathway." (PMID 37689115, 2023). "The function of ACSS2 is heavily influenced by OGT and O-GlcNAc, which are highly expressed in glioblastoma (GBM) cells." (PMID 37838167, 2023). "OGT can activate ACSS2 following Ser-267 phosphorylation, and the regulation of glioblastoma cell growth in vivo is partly dependent on this phosphorylation." (PMID 40097417, 2025). "In conclusion, our results suggest that OGT and BRD4 regulate a common set of genes involved in glioblastoma proliferation, invasion, and migration but act independently in terms of their role in transcriptional regulation." (PMID 37689115, 2023). "Here, we have investigated the role of OGT and OGA enzymes in glioblastoma cells through their chemical inhibition and gene knockdown." (PMID 37689115, 2023). "In order to investigate the mechanisms of OGT/OGA and protein O-GlcNAcylation on gene regulation in cancer, we decided to determine the effect of OGT and OGA knockdown in human glioblastoma cells." (PMID 37689115, 2023). "Moreover, drugs targeting OGT and CDK5 have demonstrated efficacy in reducing glioblastoma tumors in vitro." (PMID 39285476, 2024). "We found BRD4 to be O-GlcNAcylated in glioblastoma cells; however, OGT knockdown/inhibition neither changed its expression nor its chromatin association on promoters." (PMID 37689115, 2023).
glioblastoma (continued). "Therefore, in order to understand the role of OGT and OGA in glioblastoma, we depleted the levels of these enzymes in U87 cells by using shRNAs delivered through lentivirus." (PMID 37689115, 2023). "Thus, we believed that combined inhibition of OGT and BRD4 may have synergetic effect on glioblastoma cells." (PMID 37689115, 2023). "Thus, combined inhibition of OGT and BRD4 could be utilized as a therapeutic strategy for highly efficient glioblastoma targeting than either protein alone." (PMID 37689115, 2023). "As we found the expression of BRD4 or its recruitment on OGT target genes remains unaffected due to OGT reduction, we postulated that BRD4 inhibition along with OGT reduction may have a synergistic effect on mRNA expression of target genes, thus affecting glioblastoma cells." (PMID 37689115, 2023). "We propose BRD4 and OGT act independently in the transcriptional regulation of a common set of genes and that combined inhibition of OGT and BRD4 could be utilized therapeutically for more efficient glioblastoma cell targeting than targeting of either protein alone." (PMID 37689115, 2023).
liver fibrosis (8 papers, 2018 to 2025). "It was found that OGT-deficient hepatocytes are prone to hepatocyte ballooning, inflammation, and liver fibrosis." (PMID 36429065, 2022). "Conversely, hepatocyte-specific OGT knockout sensitizes hepatocytes to oxidative and endoplasmic reticulum (ER) stress-induced apoptosis, exacerbating liver fibrosis and injury." (PMID 41280891, 2025). "Conversely, hepatocytes with acquired O-GlcNAc modification exhibited reduced necroptosis and liver fibrosis, indicating that OGT has the potential to inhibit necroptosis in hepatocytes and suppress the advancement of liver fibrosis." (PMID 39669199, 2024). "Previous findings have shown that O-GlcNAcylation is important for normal liver physiology, and OGT-LKO mice represent an effective animal model to investigate the cellular and molecular mechanisms underlying liver fibrosis." (PMID 34146542, 2021). "The detailed role of OGT in Hif‐1 signaling cascade and in development of liver fibrosis is worthy further research." (PMID 29511617, 2018). "In current work, it was firstly determined that OGT increasingly expressed in hypoxia‐induced HSCs and in tissues of liver fibrosis." (PMID 29511617, 2018). "The increased expression of OGT was further confirmed at mRNA and protein level in hypoxia‐induced LX‐2 cells, and also in tissue samples of liver fibrosis infected by S. japonicum." (PMID 29511617, 2018). "Another study utilized a hepatocyte-conditional Ogt gene-deletion model and revealed OGT as a key suppressor of RIPK3-mediated hepatocyte necroptosis and liver fibrosis." (PMID 35185892, 2022). "OGT, a negative regulator of HSC activation, exerts a protective effect against hepatic fibrosis by boosting SRF O-GlcNAcylation." (PMID 36429065, 2022). "Liver‐specific O‐GlcNAc transferase (OGT)‐KO mice (OGT‐LKO) emerged liver injury and liver fibrosis, and increased levels of pro‐inflammatory cytokines." (PMID 35083817, 2022). "Mice lacking OGT in hepatocytes spontaneously develop liver fibrosis, which could only be partially attributed to hepatocyte necroptosis." (PMID 34146542, 2021).
cardiac hypertrophy (6 papers, 2018 to 2025). "One of the top candidates is the O-linked N-acetylglucosamine (GlcNAc) transferase (OGT), which catalyzes a common post-translational modification known for its role in heart arrhythmias and heart hypertrophy." (PMID 36345035, 2022). "Our group recently demonstrated increased cardiomyocyte size and pathological cardiac hypertrophy in a cardiomyocyte OGT overexpression model (OGT TG)." (PMID 38641064, 2024). "It was recently proposed that SA may improve cardiac hypertrophy in H9c2 cells through AMPK to reduce OGT expression, which is consistent with a recent report that AMPK improved cardiac hypertrophy by reducing OGN." (PMID 39861172, 2025). "In addition to GFAT regulation, we also ascertained a decrease in OGT protein expression after AMPK activation in our in vivo model of cardiac hypertrophy." (PMID 29371602, 2018). "In contrast to these in vitro data, it has to be mentioned that a very recent study performed by the same research group and using inducible/cardio-specific OGT-deficient mice submitted to TAC surgery revealed that OGT does not appear to be essential for cardiac hypertrophy development." (PMID 29371602, 2018). "More importantly, we demonstrate that AMPK activation prevents both cardiomyocyte hypertrophy in vitro and cardiac hypertrophy in vivo by inhibiting O-GlcNAc signaling via its actions on GFAT and OGT." (PMID 29371602, 2018). "In OGT-overexpressing transgenic mice, cardiac dysfunction was observed without significantly increased cardiac hypertrophy after TAC." (PMID 39451203, 2024).
cholangiocarcinoma (6 papers, 2015 to 2024). A carcinoma that arises from the intrahepatic biliary tree (intrahepatic cholangiocarcinoma) or from the junction, or adjacent to the junction, of the right and left hepatic ducts (hilar cholangiocarcinoma). "Researchers have employed immunohistochemistry to demonstrate that in cholangiocarcinoma tissue samples, both OGT and overall O‐GlcNAcylation levels exhibit significant elevation, while OGA levels are concurrently found to be reduced." (PMID 38116061, 2023). "The authors first mapped the N-glycome on membranes of cholangiocarcinoma cells, in which OGT was silenced, and revealed an increased level of biantennary complex and decreased high-mannose N-linked glycans." (PMID 30400201, 2018). "Moreover, high OGT expression correlates with poorer survival rates in cholangiocarcinoma patients, suggesting its potential as a valuable predictive marker for cholangiocarcinoma." (PMID 38116061, 2023). "Higher O-GlcNAcylation and OGT levels, and lower OGA levels, were observed in cholangiocarcinoma compared with those in normal bile ducts, and this change led to poor prognosis of patients with cholangiocarcinoma." (PMID 36104770, 2022). "Studying cholangiocarcinoma, Phoomak and collaborators previously showed that high glucose stimulates the expression of hexokinase-2, the HBP rate-limiting enzyme GFAT, and OGT, contributing to the metastatic properties of these cells through elevated levels of O-GlcNAcylation." (PMID 30400201, 2018).
ischemia (6 papers, 2015 to 2024). A hypoperfusion of the BLOOD through an organ or tissue caused by a PATHOLOGIC CONSTRICTION or obstruction of its BLOOD VESSELS, or an absence of BLOOD CIRCULATION. "Previous studies have showed that cardiomyocyte OGT or O-GlcNAcylation was essential for cardiac function at both the basal level and under stress such as ischemia, and the loss of OGT promoted cardiomyocyte's apoptosis." (PMID 32850000, 2020). "We did detect a negative correlation between the AMP:ATP ratio and OGT activity consistent with a reduction in OGT activity during ischemia." (PMID 37949223, 2023). "To begin to understand the mechanisms regulating O-GlcNAc cycling, we examined the abundance of the O-GlcNAc-cycling enzymes (OGT, OGA, and GFAT2), OGT and OGA activity, and UDP-GlcNAc levels in hearts, either after 20 min of ischemia or after 120 min of reperfusion." (PMID 37949223, 2023). "Because there was no concurrent elevation of OGT or decrease of OGA, this dynamic increase in O-GlcNAcylation might be caused by an acute stress response of the brain to severe ischemia." (PMID 26412745, 2015).
leukemia (6 papers, 2014 to 2024). A malignant (clonal) hematologic disorder, involving hematopoietic stem cells and characterized by the presence of primitive or atypical myeloid or lymphoid cells in the bone marrow and the blood. "To evaluate the role of OGT in leukemia progression, we examined the impact of OGT loss or inhibition on leukemic cell growth." (PMID 38609495, 2024). "We found that 8 genes overlapped, and O-GlcNAc transferase (OGT) and ETNK1 were associated with mitochondrial function and leukemia cell survival." (PMID 38609495, 2024). "Given that a broad range of metabolic enzymes are targets of O-GlcNAcylation, the metabolic status in leukemia cells is likely finely regulated by the balance between OGT and OGA expression and activity." (PMID 38609495, 2024). "To investigate OGT’s role in the regulation of mitochondrial function mediated by TRAF6 in leukemia, we utilized a lentiviral system to overexpress OGT in TRAF6 knockdown human leukemic cells, examining its impact on growth capacity." (PMID 38609495, 2024). "This led us to investigate OGT as a mediator of TRAF6-regulated mitochondrial function in leukemia cells." (PMID 38609495, 2024). "In various cancer cell lines, the expression levels of OGT and OGA rank first and second in myeloma and leukemia, respectively; in tumor samples from the TCGA database, the expression of OGT and OGA in LAML was much higher than that in other cancers." (PMID 36104770, 2022). "Our findings highlight the oncogenic function of TRAF6 in leukemia and illuminate the novel TRAF6/OGT/O-GlcNAc axis as a potential regulator of metabolic reprogramming in leukemogenesis." (PMID 38609495, 2024).
viral infection (6 papers, 2020 to 2025). "While this experiment demonstrated that A4 sequences are recognized as substrates by OGT, it was necessary to prove this enzyme regulates O-GlcNAcylation of A4 during a virus infection." (PMID 40407344, 2025). "We identified an unexpected decreased in the transcription of OGT in response to virus infection; this resulted in the global reduction of cellular O-GlcNAcylation and the specific reduction of the O-GlcNAcylation of MAVS." (PMID 33603735, 2020). "The host cell responds to virus infection by shutting down the expression of OGT." (PMID 33603735, 2020). "However, we are not aware of any reports that describe host-mediated regulation of OGT transcription in response to viral infection." (PMID 33603735, 2020). "Therefore, targeting the activity of OGT or OGA using pharmacological inhibitors may constitute a potential therapy for viral infections, inflammatory diseases, and cancers." (PMID 36473120, 2023). "As the occurrence of cardiovascular events during COVID-19 suggests that targeting the endothelium is part of the viral infection course, we surmise COVID-19 patients who have a pre-existing genetic propensity for low SON, OGT, and RORA expression may therefore be more susceptible to cardiac damage." (PMID 33240937, 2020). "NKT cells of the peripheral blood in C. carbonaria were identified by PITPNM2, OGT, PRPF4B, PNISR, and CD3E genes, which had immunoregulatory roles in virus infection and cancer." (PMID 36552787, 2022).
acute myeloid leukemia (5 papers, 2019 to 2025). Acute myeloid leukemia (AML) is a group of neoplasms arising from precursor cells committed to the myeloid cell-line differentiation. "Previous studies by our team have shown that high expression of OGT is positively associated with poor prognosis in acute myeloid leukemia (AML)." (PMID 40389445, 2025). "Elevated level of O-GlcNAc and/or increased expression of OGT transcripts was also found in acute myeloid leukemia (AML) and in chronic lymphocytic leukemia (CLL)." (PMID 31466420, 2019). "Intriguingly, GFPT1-driven O-GlcNAcylation also modulates AKT activation, as lower O-GlcNAcylation levels, induced by pharmacological inhibition of GFPT1 or OGT, correlate with heightened AKT phosphorylation at Ser473 and Thr308 in acute myeloid leukemia (AML) cells." (PMID 40830088, 2025).
Alzheimer disease (5 papers, 2018 to 2025). A progressive, neurodegenerative disease characterized by loss of function and death of nerve cells in several areas of the brain leading to loss of cognitive function such as memory and language. "For example, exposure of neuronal cells to amyloid-beta (Aβ), a hallmark protein of Alzheimer’s disease, leads to reduced O-GlcNAcylation due to S-nitrosylation-induced OGT inactivity." (PMID 41146299, 2025). "While some OGA inhibitors are already in phase 1 clinical trials for the treatment of Alzheimer’s disease, OGT inhibitors still have a long way to go." (PMID 33669256, 2021). "OGT is positively correlated to citrate synthase protein levels, lactate dehydrogenase (LDH) activity and postsynaptic density protein 95 (PSD95), which is an important postsynaptic scaffolding protein and decreased levels are associated with Alzheimer disease pathology." (PMID 35248135, 2022).
cardiomyopathy (5 papers, 2021 to 2025). A disease of the heart muscle or myocardium proper. "Given the significant impact of ISRIB against the development of OGT-cardiomyopathy, we sought to investigate the molecular changes that underlie this effect." (PMID 41101503, 2025). "As loss of OGT leads to HF, we examined the efficacy of ISRIB in preventing cardiomyopathy in OGT-deficient mice." (PMID 41101503, 2025). "Genetic testing revealed two variants of uncertain significance (VUSs): LMNA c.1634 G>A, p.(R545H), initially linked to cardiomyopathy but later reclassified as non-pathogenic, and OGT c.3040 A>G, p.(M1014V)." (PMID 39706180, 2025). "Interestingly, a balanced cardiomyocyte OGT activity needs to be kept, because mice with cardiac overexpression of OGT throughout embryonic and postnatal development exhibit cardiomyopathy by early adulthood." (PMID 36642184, 2023). "The experiment also found that although the amount of OGT in the heart muscle of mice is increasing, if OGT is crossed with OGA transgenic mice, cardiomyopathy and premature death can be saved." (PMID 38116061, 2023).
developmental delay (5 papers, 2019 to 2025). "To date, XLID-associated mutations in the OGT gene have only been reported for male patients, causing developmental delay and severe cognitive disability." (PMID 31296563, 2019). "Here, we characterize an OGT missense mutation in the catalytic domain as observed in female twins with ID and developmental delay." (PMID 31296563, 2019). "All patients display developmental delay, an IQ < 80 and a degree of facial dysmorphia, suggesting that different mutations in OGT could have a similar etiology." (PMID 41033462, 2025). "Furthermore, knocking down OGA in mouse brain leads to microcephaly, hypotonia, and developmental delay, suggesting a possible link between OGT-XLID variants and perturbations of OGA levels." (PMID 32080367, 2020). "Analogous to previously reported OGT-CDG mutations, patients carrying the OGTC921Y variant present with a broad array of phenotypes, including developmental delay, brain abnormalities and musculoskeletal defects." (PMID 37334838, 2023). "Thirteen affected individuals from seven families presenting with previously unclassified ID and developmental delay were subjected to genetic testing and found to carry nonsynonymous variants in the OGT gene (NM_181672.2, GenBank) located on the X chromosome." (PMID 32080367, 2020).